ALG10B (ALG10 alpha-1,2-glucosyltransferase B)
Description:
Dol-P-Glc:Glc(2)Man(9)GlcNAc(2)-PP-Dol alpha-1,2-glucosyltransferase that operates in the biosynthetic pathway of dolichol-linked oligosaccharides, the glycan precursors employed in protein asparagine (N)-glycosylation. The assembly of dolichol-linked oligosaccharides begins on the cytosolic side of the endoplasmic reticulum membrane and finishes in its lumen. The sequential addition of sugars to dolichol pyrophosphate produces dolichol-linked oligosaccharides containing fourteen sugars, including two GlcNAcs, nine mannoses and three glucoses. Once assembled, the oligosaccharide is transferred from the lipid to nascent proteins by oligosaccharyltransferases. In the lumen of the endoplasmic reticulum, adds the third and last glucose residue from dolichyl phosphate glucose (Dol-P-Glc) onto the lipid-linked oligosaccharide intermediate Glc(2)Man(9)GlcNAc(2)-PP-Dol to produce Glc(3)Man(9)GlcNAc(2)-PP-Dol.
Synonyms: KCR1; ALG10
Tractability: Antibody: its Gene Ontology location is reachable by antibodies, with high confidence; UniProt predicts a signal peptide or a membrane-spanning region. PROTAC: ubiquitination databases record sites on it; its protein half-life has been measured.
Gene: Protein-coding gene on chromosome 12 (38,316,762 to 38,329,721, forward strand). Ensembl gene ENSG00000175548.
Subcellular location: Endoplasmic reticulum membrane
Subcellular location (Human Protein Atlas): Endoplasmic reticulum
Pathways (Reactome):
Metabolism of proteins: Biosynthesis of the N-glycan precursor (dolichol lipid-linked oligosaccharide, LLO) and transfer to a nascent protein
Gene Ontology:
Molecular function: dolichyl pyrophosphate Glc2Man9GlcNAc2 alpha-1,2-glucosyltransferase activity; protein binding
Biological process: dolichol-linked oligosaccharide biosynthetic process; protein N-linked glycosylation
Cellular component: endoplasmic reticulum membrane; plasma membrane; lumenal side of endoplasmic reticulum membrane
Genetic constraint (gnomAD): Loss-of-function variants: 27 observed, 36.59 expected, observed/expected ratio (o/e) 0.74, 90% interval 0.54 to 1.02. The upper end of that interval is the gene's LOEUF score, 1.02, which puts it in group 4 of 6, group 1 being the genes least tolerant of losing a copy. Missense variants: 511 observed, 531.15 expected, observed/expected ratio (o/e) 0.96, 90% interval 0.89 to 1.03. Synonymous variants: 168 observed, 189.65 expected, observed/expected ratio (o/e) 0.89, 90% interval 0.78 to 1.01.
Gene-disease validity (ClinGen):
ClinGen rates the evidence that ALG10B causes each of these diseases.
long QT syndrome (autosomal dominant): Limited.
Homologues: Orthologues: chimpanzee ALG10B (97% identical), macaque ALG10 (96% identical), rat Alg10 (86% identical), mouse Alg10b (85% identical), tropical clawed frog alg10 (56% identical), zebrafish alg10 (55% identical), Drosophila melanogaster Alg10 (32% identical), Caenorhabditis elegans algn-10 (30% identical). Paralogues in human: ALG10 (96% identical).
Diseases named in the same sentence as ALG10B in open-access papers:
ALG10B is named in the same sentence as 6 diseases in open-access papers, as found by Europe PMC text mining. Sharing a sentence is not in itself a finding about the gene and the disease. The quoted sentences say what the papers report.
acquired long QT syndrome (2 papers, 2011 to 2024). A form of long QT syndrome in which malfunction of the cardiac ion channels is caused by drugs or metabolic abnormalities. "Polymorphisms on ALG10B are associated with the risk of acquired long QT syndrome, a cardiac rhythm disturbance." (PMID 21291537, 2011).
Hearing impairment (1 paper, 2013). A decreased magnitude of the sensory perception of sound. "First, ALG10B mutations in humans may cause nonsyndromic hearing impairment, as opposed to a multisystem disease, which would explain why no ALG10B mutations have previously been detected in a patient with a suspected CDG." (PMID 24303013, 2013). "Needless to say, yeast is not traditionally thought of as a model organism for hearing impairment, but the bulk of the research on ALG10B has been carried out in yeast." (PMID 24303013, 2013).
insomnia (1 paper, 2024). A sleep disorder characterized by difficulty in falling asleep and/or remaining asleep. "In the realm of sleep and circadian health, reported genetic associations corroborated the relevance of EFNA5, ZNF521, WWOX, ALG10B, PAM and SDK1 with insomnia, daytime napping, or chronotype traits." (PMID 39070651, 2024).
long QT syndrome (1 paper, 2024). "ALG10B was identified to be implicated in the Mendelian disorder long QT syndrome." (PMID 39070651, 2024).
ALG10B also shares sentences with these, for which no sentence is quoted: Nonsyndromic Hearing Impairment (1 paper); Sepsis (1).